CD34 (CD34 molecule)
Diseases named in the same sentence as CD34 in open-access papers (continued):
Sharing a sentence is not in itself a finding about the gene and the disease.
cancer (continued). "The presence of CHIP was associated with a history of smoking (p = 0.04), past medical history of cancer (p = 0.04) and a decreased efficiency of stem cell mobilization (5.8 million CD34+ cells/kg/day in those with CHIP compared to 8.3 million CD34+ cells/kg/day in those without CHIP (p = 0.03)." (PMID 32533060, 2020). "An immunophenotypic analysis revealed that ZJU-0430 cells were positive for CD24, CD44, CD29 and CD133 expression, and partially positive for CD184, and CD326 expression, and negative for CD34, CD90, CD117, and CD338 expression, similar to the primary cancer cells." (PMID 31367188, 2019). "Although not previously shown to be directly related with cancers, several surface markers, such as CD19 and CD34, showed significant positive correlation (Pearson R > 0.5) with RUNX1T1 in RNA levels, whereas CD33 showed negative correlation (Pearson R = −0.36)." (PMID 30959925, 2019). "Malignant GIST usually expresses CD117, Dog-1 and CD34, which were all negative in this case." (PMID 28472972, 2017). "Here we show that T-LAK cell-originated protein kinase (TOPK), a mitotic kinase highly expressed in and correlated with more aggressive phenotype in several types of cancer, is expressed in AML but not in normal CD34+ cells and that TOPK knockdown decreased cell viability and induced apoptosis." (PMID 26450903, 2015). "Besides, all the three cell lines were negative for CD34 antigen but they evidenced equal strong positivity for CD29, CD44 and CD90, mesenchymal and cancer stem cells markers." (PMID 18941626, 2008). "Furthermore, we showed that Ova alone or by enhancing the therapeutic potential of Imatinib, reduced the viability of CML cell lines, dose-dependently, irrespective of the cancer stemness, as well as markedly inhibit the Bcr-Abl, p-CrkL, Stat5, and MDR protein expression levels in CD34+ cells." (PMID 29423045, 2018).
infection (231 papers, 2005 to 2026). The state of being infected such as from the introduction of a foreign agent such as serum, vaccine, antigenic substance or organism. "We have previously shown that HCMV-encoded miRNAs play significant roles in CD34+ HPC infection and can disrupt signaling pathways necessary for efficient reactivation from latency." (PMID 39661658, 2024). "There was also a reduction of cord blood CD34+ progenitors in women at term who recovered from the infection, that the authors linked to an increased susceptibility to IFN-γ-mediated apoptosis in these cells." (PMID 38082066, 2023). "Ex-vivo T-cell depletion (e.g., with CD34+ selection) is associated with excess risks of infection, NRM, and possibly relapse." (PMID 36741737, 2022). "While all three humanized mouse strains were susceptible to VARV and supported a productive infection, the more advanced hu-CD34+ and hu-BLT mice are the best candidates for further model characterization." (PMID 34547055, 2021). "Mechanistically, little had been uncovered to account for the global suppression caused by infection of only a small number of CD34+ HPCs, until a recent study examining the regulation of TGF-β." (PMID 34025614, 2021). "The risk factors for CD34+ PBMCs infection byM.tb (proximal factors) are grounded in the presence of a quiescent BM environment forM.tb persistence." (PMID 32832853, 2020). "In order to support the practical utility of the mutated CCR5 MSCs, we next converted the mutated cells to CD34+ cells by infection with a retrovirus encoding Oct4." (PMID 25890320, 2015). "CD34+ HP/HSCs are susceptible to infection with a number of viruses including HIV-1, HTLV-1, Hepatitis C virus, JC virus, Parvovirus, Human Cytomegalovirus (HCMV), and the Human Herpesviruses (HHV): HHV-5, HHV-6, HHV-7, HHV-8." (PMID 20132553, 2010). "Prospective studies could clarify the minimal CD34+ cell dose required, and evaluate long-term outcomes, including immune reconstitution and infection risk." (PMID 41561742, 2025). "Larger cohorts will be needed to more robustly investigate associations between CD34+ cell dynamics, infection, and prematurity-related morbidities, as well as to evaluate the impact of interventions and clinical factors such as blood transfusion, timing of cord clamping, and sampling frequency." (PMID 41147034, 2025). "It is possible that infection will cause a change that will convert CD133+ to CD34+ and vice versa." (PMID 37386042, 2023). "Gene therapy in human CD34+ HSPCs could prevent the infection of susceptible cells because HSPCs give rise to all blood cell types in HIV-1 pathogenesis, including CD4+ T cells, macrophages, dendritic cells, and microglia." (PMID 35216446, 2022). "Apart from the immunocompromised rodents, a lethal humanized mouse model transplanted with human hematopoietic CD34+ stem cells and an immunocompetent mouse model which developed disease following infection with a mouse-adapted variant of CCHFV have been reported." (PMID 34206476, 2021). "Furthermore, the loss of LSK CD150+ CD34- CD48- Ki67- cells during infection represented a 24-fold decrease in number (from 831 ± 0.017 to only 34.62 ± 31.93 cells in total BM)." (PMID 28671989, 2017). "It has indeed been previously reported that Rag2−/−γc−/− mice conditioned with TBI and transplanted with human CD34+ cells sustain high-titer infection persisting more than one year and associated with a slower decline of CD4 T cells after inoculation of an R5 strain." (PMID 22675567, 2012). "M1 and U1 vectors efficiently transduced human fetal liver-derived CD34+ HSPC (FL-CD34+ HSPC) at multiplicity of infection (MOI) 3 ex vivo." (PMID 40503012, 2025). "It is important to note that the use of a single batch of CD34+HSCs for cell transplantation limited the diversity of transplant combinations, affecting subsequent infection analyses." (PMID 40102849, 2025).
infection (continued). "As a pooled population, latently infected CD34+ cells transcribe the full complement of genes expressed during lytic infection, although at much lower levels." (PMID 40736257, 2025). "Despite these limitations, under similarly restrained replication levels (right), the suppressive effect on human CD34+ precursors and the impact on mouse survival (right) were more severe in MVMp than in MVMi infections." (PMID 41143413, 2025). "The CD34+ HPC infection model also has inherent donor-to-donor variability that can affect reproducibility and complicate statistical analyses." (PMID 40736257, 2025). "We then constructed an adenovirus expressing Pdgfra (Ad‐Pdgfra), Pdgfrb (Ad‐Pdgfrb), and an Ad‐vector to infect adventitial CD34+ cells, achieving high overexpression levels with an infection titer of 108PFU mL−1." (PMID 39731355, 2025). "Eight litters of mice were used to obtain a sufficient number of mice for statistically valid results, with similar numbers, and levels of CD34+ cells in mice within each litter allocated for infection with HTLV-1-WT, HTLV-1-p12stop, or HTLV-1-CTCF." (PMID 40460345, 2025). "The long-term or permanent expression of anti-HIV genes and the modification of CD4+ and CD34+ cells to render them resistant to infection or to allow the disruption of the HIV life cycle are important strategies in the quest to achieve a HIV cure." (PMID 38474018, 2024). "Eight litters of mice were used to obtain a sufficient number of mice for statistically valid results, with similar numbers, sexes, and levels of CD34+ cells in mice within each litter allocated for infection with HTLV-1-WT, HTLV-1-p12stop, or HTLV-1-CTCF." (PMID 38853836, 2024). "CD34+ HPCs were engrafted into NOD-scidIL2Rγcnull mice (huNSG) followed by infection with WT HCMV or ΔmiR-UL36/112/148D." (PMID 39661658, 2024). "cd34 expression was downregulated relative to the control group in all compartments during the first 5 weeks of infection." (PMID 39759525, 2024). "It is well established that infection of CD34+ progenitors and CD14+ monocytes with HCMV in which US28 has been deleted not only results in IE gene expression, but also in the production of infectious virus." (PMID 38287192, 2024). "Consistent with this, we observed decreased Akt phosphorylation in response to EGF stimulation during infection of fibroblasts and hESC-derived CD34+ HPCs with WT HCMV." (PMID 39661658, 2024). "Infection of hESC-derived CD34+ HPCs with the ΔmiR-UL36/112/148D mutant infected cells showed a significant decrease (p<0.0001) in the frequency of infectious center production compared to WT infected cells." (PMID 39661658, 2024). "The failure of ΔUL138STOP to enter latency is reflected in increased viral genome synthesis in CD34+ HPCs relative to the WT infection." (PMID 37289831, 2023). "Although dengue virus (DENV) can establish infections in hematopoietic stem progenitor cells (HSPCs), there is little information on dengue virus persistent infection in CD34+ and CD133+ cell surface glycoproteins of hematopoietic stem cells (HSCs)." (PMID 37386042, 2023). "On one hand, the high expression of TLR on CD34+ cells suggests that the expression of TLR on HSCs is an early sensory mechanism for HSCs to directly detect infection and immediately generate immune effector cells." (PMID 36674552, 2023). "Here we study this concept through an investigation of the interaction of human cytomegalovirus (HCMV) with CD34+ hematopoietic progenitor cells during the very early stages of cell infection." (PMID 37080390, 2023). "Pertinently, it has been demonstrated that HCMV dramatically alters the host miRNAome during lytic infection and during long-term latent infection of CD34+ cells." (PMID 37080390, 2023). "To better understand this phenomenon, we examined the susceptibility of CD133 and CD34 cells in UCB towards DENV and their proliferative capacity using a Brdu proliferation assay after prolonged infection." (PMID 37386042, 2023).
infection (continued). "Human cytomegalovirus (HCMV) latency in CD34+ progenitor cells is the outcome of a complex and continued interaction of virus and host that is initiated during very early stages of infection and reflects pro- and anti-viral activity." (PMID 37080390, 2023). "In vitro infection of CD34+ HPCs with HHV-6 suppresses hematopoietic colony formation of granulocyte-macrophage, erythroid, and megakaryocyte lineages." (PMID 37346032, 2023). "The dataset reveals changes in the miRNAome that occur upon infection of primary CD34+ hematopoietic cells with HCMV." (PMID 37080390, 2023). "Conversely, once HCMV infects undifferentiated cells of the myeloid lineage, such as CD34+ hematopoietic progenitor cells (HPCs), the infection becomes latent." (PMID 37439556, 2023). "Our next objective was to determine the association of CD34 and CD133 with NS1 after prolonged infection at various time points (days 5, 10, 14, 21, 25, and 30)." (PMID 37386042, 2023). "Here, we show that CD34+CD90+ HSCs are limited with HIV receptor/co-receptor, express increased amount of antiviral restriction factors and exhibit resistance to R5-tropic infection, making the CD34+CD90+ HSCs ideal target cells for CCR5 manipulation." (PMID 35359982, 2022). "HCMV miR-US5-1 and miR-UL112-3p target the proapoptotic transcription factor FOXO3a after infection of CD34+ HPCs, resulting in reduced expression of the proapoptotic BCL2L11 transcript." (PMID 35746686, 2022). "Active infection was considered as the strongest predictor of the efficacy of CD34+-selective infusion, possibly because of the impaired immune microenvironment caused by inflammation." (PMID 35720412, 2022). "An additional study demonstrated the importance of interferon-stimulated genes in limiting the infection of CD34+ cells by HIV-1." (PMID 36230931, 2022). "Cross-species confirmation using human BM aspirates from three different healthy donors confirmed heavy VL infection of hHSPC (CD45lo CD34+) after in vitro infection comparable to the observations in mouse LT-HSC." (PMID 35752645, 2022). "In contrast, in vitro infection with R5 HIV-1 was only achieved in CD34+CD38+ progenitors and to a significantly lower extent compared to X4." (PMID 36230931, 2022). "Umbilical cord blood (UCB) transplantation is performed less frequently in the adult population due to concerns regarding low CD34+ stem cell dose, delayed engraftment, and heightened risks of infection and NRM." (PMID 36741737, 2022). "HCMV latency is established when infected monocytes traffic to the bone marrow and spread infection to a small number of CD34+ hematopoietic progenitor cells (HPCs)." (PMID 35214602, 2022). "In a recent study, we demonstrated that NSG-A2 mice engrafted with human hematopoiesis via the transplantation of CD34+ human HSCs recapitulated the case-fatality ratios of ebolaviruses in humans after experimental infection." (PMID 36073921, 2022). "We also show that these newly generated viruses in the TB40/E background support the infection of hematopoietic cells, including primary cord blood-derived CD34+ HPCs and the CD34+ cell line, Kasumi-3 cells." (PMID 35746751, 2022). "These FA-like cells were generated by infection of CD34+ cord blood cells with a lentivirus expressing a shRNA against FANCD2." (PMID 36441774, 2022). "We next forced LncSIK1 expression in human CD34+ HSPCs by infection with lentiviral LncSIK1‐WT plasmids." (PMID 35092119, 2022). "Clinical manifestations include myelosuppression and graft rejection as a result of infection of CD34+ HPCs." (PMID 34025614, 2021). "EGFR is a well-studied viral entry receptor that contributes to the establishment of efficient infection and latency of both monocytes and CD34+ HPCs." (PMID 34663377, 2021).
infection (continued). "Human cytomegalovirus (HCMV) infection of myeloid lineage cells, such as CD34+ hematopoietic progenitor cells (HPCs) or monocytes, results in the upregulation of antiapoptotic cellular proteins that protect the newly infected cells from programmed cell death." (PMID 33408225, 2021). "Like infection of monocytes, initial infection of CD34+ HPCs relies on receptor-ligand engagement with EGFR engagement being key to early infection." (PMID 34025614, 2021). "HCMV-infected CD34+ HPCs not only show significant reduction in proliferation, but specific myeloid differentiation programs are also blocked by infection." (PMID 33668486, 2021). "Infection of CD34+ HPCs with miR-UL22A-deficient virus also resulted in a lower frequency of reactivation relative to wild type virus, while infection with miR-UL22A-deficient/SMAD3 shRNA virus restored reactivation potential." (PMID 34299120, 2021). "After an initial acute infection, HCMV establishes latency in CD14+ monocytes and CD34+ hematopoietic progenitor cells (HPCs), resulting in lifelong infection of the host (3, –, 7)." (PMID 33824207, 2021). "Both the miRNAs and UL7 are expressed at early times post-infection of CD34+ HPC and reduce FOXO3a levels and activity to limit the induction of apoptosis in this cell type." (PMID 33668486, 2021). "To identify the tissue reservoir of infected human CD4+ T cells after i.p. infection in CD34 mice, we used RNAscope to visualize HIV-1 RNA in spleen and GALT (ileum and colon) sections." (PMID 33673566, 2021). "In contrast to a quiescent infection of monocytes during a primary infection, long-term maintenance occurs in latently infected CD34+ HPCs and requires an external activation stimulus for reactivation into lytic replication." (PMID 34663377, 2021). "For this review and for infection of monocytes and CD34+ HPCs, gB engagement of EGFR is essential for entry and the post entry events related to nuclear translocation as well as for the associated downstream signaling." (PMID 34025614, 2021). "Despite the known expression of receptors such as NRP-2, THY-1, CD147, and CD151 on myeloid cells, the contribution of these HCMV entry receptors to infection of monocytes or CD34+ HPCs have yet to be thoroughly examined." (PMID 34663377, 2021). "Here, we show that HCMV utilizes pUL7, a secreted protein that signals through the FLT3 receptor, and miR-US5-1 and miR-UL112-3p to reduce the abundance and activity of the proapoptotic transcription factor FOXO3a at early times after infection of CD34+ HPCs." (PMID 33408225, 2021). "Here, we show that both a viral protein and viral miRNAs are required to prevent apoptosis after infection of CD34+ HPCs." (PMID 33408225, 2021). "There is evidence of HCV infecting HSC and measles virus suppressing HSC through direct infection of CD34." (PMID 33981874, 2021). "CXCR4-using viruses can also interfere with the replenishment of naive cells through depletion of thymocytes and infection of CD34+ multipotent hematopoietic progenitor cells in the bone marrow (BM)." (PMID 33872329, 2021). "We found that the expression of TER119+CD34+ cells in the bone marrow of pregnant mice was decreased significantly after infection with E. coli compared with healthy pregnant mice." (PMID 34220146, 2021). "Next, we extended our analysis to evaluate the time-related variation in subsets levels of CD133+/- CD34+/−NS1+ cells in DENV-infected UCB at a different stage of infection to show the kinetic of cell content." (PMID 33981874, 2021). "EGFR and downstream PI3K signaling are also important to mediate infection that leads to establishment of latency in CD34+ cells." (PMID 34831300, 2021). "The establishment of a persistent infection in both monocytes and CD34+ HPCs is critical for viral dissemination and life-long persistence within an infected host." (PMID 34663377, 2021).